INS (insulin)
Diseases named in the same sentence as INS in open-access papers (continued):
Sharing a sentence is not in itself a finding about the gene and the disease.
metabolic disorders (continued). "Detailed reviews about insulin signaling and its implication in proteostasis and metabolic disorders can be found elsewhere." (PMID 33398091, 2021). "Then, treatment with 10–6 mol/L of insulin for 24 h was selected to establish metabolic disorder model in HepG2 cells." (PMID 33981226, 2021). "The elevation of FGF21 levels in metabolic disorders has been inferred as a compensatory response to attenuate glucose and lipid dyshomeostasis via exerting insulin-sensitizing and triglyceride-lowering effects." (PMID 33668309, 2021). "DM is a systemic metabolic disease characterized by abnormal insulin production and/or insulin action over time, resulting in high blood sugar." (PMID 34206139, 2021). "One of the multiple disruptions during the development of metabolic diseases take place in skeletal muscle, where insulin signaling, glucose uptake, lipid metabolism, and mitochondria become dysfunctional." (PMID 33433056, 2021). "Type 2 diabetes (T2D), which has currently become a global pandemic, is a metabolic disease largely characterised by impaired insulin secretion and action." (PMID 34413662, 2021). "With this approach, syntaxins, a group of proteins involved in insulin exocytosis, were identified as relevant PTS interactors and used as a probe to give information on the potential role of PTS in insulin-based metabolic diseases." (PMID 32585851, 2020). "Different studies have demonstrated that PDE5i, by sensitizing insulin target tissues to insulin, play an important role in controlling the action of insulin and glucose metabolism, highlighting the protective action of these drugs against metabolic diseases." (PMID 32774364, 2020). "T2D is a metabolic disease characterized by impaired cellular signaling that affects insulin secretion in pancreatic beta cells and impedes insulin signaling and energy homeostasis at specific peripheral target tissues." (PMID 33349332, 2020). "Altogether, while the lifespan of WT flies was completely rescued on the 20%S + H2O condition to that of “healthy” controls, they remained obese, hyperglycemic, and insulin resistant, which are hallmarks of metabolic disease." (PMID 32197072, 2020). "Systemic metabolic disorders disrupt insulin functions and inhibit activation of insulin receptors in hippocampus." (PMID 32575897, 2020). "In contrast, hepatocyte-specific knockout of Mettl3 significantly alleviated HFD-induced metabolic disorders by slowing weight gain, reducing lipid accumulation, and improving insulin sensitivity." (PMID 33160098, 2020). "In both human and pigs, increased desaturation index and SCD1 activity have been related to metabolic disorders, like alterations in lipogenesis and insulin regulation, in which peroxisome proliferator-activated receptors (PPARs) have a prominent role." (PMID 32932852, 2020). "Blocking of inflammation with a TNFα antagonist during rheumatoid arthritis increases sensitivity to insulin, indicating a link between inflammation and metabolic disorders." (PMID 33333870, 2020). "Inhibition of HDACs has been demonstrated to increase insulin secretion and prevent metabolic disorders." (PMID 32581784, 2020). "Due to its role in adipocyte differentiation, lipid metabolism, glucose homeostasis, insulin sensitivity, and, more recently, in inflammatory and immune responses, PPARγ represents an attractive pharmacological target to address metabolic disorders." (PMID 32138197, 2020). "Taken together, SA relieves metabolic disorders by inhibiting body weight increases, reducing fasting blood glucose levels, and ameliorating insulin tolerance in HFD-induced obese mouse models." (PMID 32218700, 2020). "DM is a group of metabolic diseases characterized by chronically increased glucose levels resulting from defects in insulin secretion and/or insulin action." (PMID 32742520, 2020).
metabolic disorders (continued). "Type 2 DM (DM-II) accounts for 90–95% of all DM cases and is a progressive metabolic disorder characterized by resistance to insulin effects and abnormal insulin production to maintain blood glucose levels, presenting a complex and multifactorial etiology." (PMID 32715137, 2020). "Since AD has many characteristics in common with impaired insulin signaling pathways, AD can be regarded as a metabolic disease." (PMID 32083135, 2020). "A great importance of FFA in metabolic disorders results from the fact that it promotes IRes development by interacting with the insulin signal pathway." (PMID 33322719, 2020). "How does IP6K1 mediated enhancement in insulin secretion and inhibition in insulin signaling fit in the context of metabolic diseases?" (PMID 32204420, 2020). "In both human and pigs, increased desaturation index and SCD1 activity have been related to metabolic disorders, like alterations in lipogenesis and insulin regulation." (PMID 33291637, 2020). "Various natural substances have been shown to govern any cardiovascular or metabolic disorders through different mechanisms, such as triggering anti-inflammation, lipid profile correction, sensitization of insulin reception, or blood glucose control." (PMID 32435657, 2020). "Activation of FFAR2 by SCFAs regulates metabolic disorders, increases energy expenditure, and preferentially enables fat consumption by inhibition of insulin signaling in adipose tissues." (PMID 32963827, 2020). "S. Kumpatlaetal, observed that ‘DM-TB’ group were more likely to have metabolic disease, (>10 years), to be on combination therapy with oral and insulin medication and have higher HB1AC levels (>7)." (PMID 32502176, 2020). "Regular physical activity has been shown to improve insulin sensitivity and thus, enhance metabolic functions in individuals suffering from metabolic disorders like T2DM." (PMID 32481704, 2020). "Females with intact ovaries who are more insulin sensitive are protected from metabolic disorders because their BAT ratio is higher than the total fat." (PMID 32309765, 2020). "Some studies have recently demonstrated that Aβ and tau cannot fully explain the pathophysiological development of AD and that metabolic disease factors, such as insulin, adiponectin, and antioxidants, are important for the sporadic onset of nongenetic AD." (PMID 32899357, 2020). "Insulin sensitivityis higher in females than in males, and males show a greater tendency to develop metabolic disorders." (PMID 33659826, 2020). "Our group suspects that some patients secrete insulin with adequate biological activity based on affected organogenesis pathways and pancreatic insulin synthesis, and that their hepatic insulin sensitivity is sufficient to avoid metabolic disorders." (PMID 32864159, 2020). "Overall, studies have observed encouraging therapeutic potential of liver-specific ROCK1 inhibition in metabolic disease models, demonstrated by increased energy expenditure, improved insulin sensitivity, and attenuated lipid accumulation." (PMID 33633690, 2020). "Beta cells serve to prevent metabolic diseases by biosynthesizing and secreting insulin to maintain glucose homeostasis." (PMID 33182622, 2020). "Conversely, SFA values and the ratio of Σn−6/Σn FA decreased, which is protective against metabolic disorders by diminishing pro-inflammatory status and favoring the action of insulin." (PMID 32429595, 2020). "Maternal exercise markedly improved insulin sensitivity in dams and metabolic disorders in offspring from young into adulthood." (PMID 32626663, 2020). "The expression of this gene can be regulated by insulin, glucocorticoids, glucagon, cAMP, and diet and it has multiple relationships with several metabolic diseases." (PMID 32957918, 2020).
metabolic disorders (continued). "Patients who are unable to make enough insulin are additionally treated with insulin dosages whereas those patients whose cells are unable to respond properly to insulin are treated with different drugs, developed to cure carbohydrate-metabolism disorders." (PMID 33118125, 2020). "World health organization defined DM as a metabolic disorder of multiple etiology characterized by chronic hyperglycemia with disturbances of carbohydrate, fat and protein metabolism resulting from defects in insulin secretion, insulin action, or both." (PMID 32015875, 2020). "Overall, our findings show the importance of visualizing health as a network of organs and/or systems, and highlight the importance of triglycerides, insulin, uric acid and glucose as key biomarkers in the prevention of the development of metabolic disorders." (PMID 33117199, 2020). "Diabetes is a metabolic disease characterized by glucose, protein, fat, and other metabolic disorders that occur due to hypofunction of islets of Langerhans and insufficient insulin secretion." (PMID 32182870, 2020). "Individuals with MetS display a characteristic imbalance of their adipokine profile, which leads to changes in insulin sensitivity and biochemical alterations of metabolites, making an individual more prone to metabolic disorders." (PMID 32899507, 2020). "This work establishes a functional crosstalk between bacteria-derived peptidoglycan and the immune NF-κB cascade that contributes to the onset of metabolic disorders by reducing insulin signal transduction." (PMID 32839462, 2020). "The overpresentation of GH, insulin, IGF-1, or IGF-2 signaling is associated with severe metabolic diseases, overgrowth, and obesity." (PMID 33333870, 2020). "The elucidation of the molecular mechanisms mediating insulin signalling is therefore essential for the development of therapeutic strategies to treat metabolic disorders." (PMID 32249683, 2020). "DKD is a metabolic disorder which is characterized by renal damage due to deterioration in insulin secretion or insulin activity." (PMID 31534972, 2019). "In recent years, FGFs have received increasing attention for their unexpected role in metabolic disease and for their potential to treat metabolic disorders by helping restore insulin sensitivity." (PMID 30695023, 2019). "The amount of skeletal muscle mass indicates the ability to respond to insulin, which in turn is a major predictor of metabolic diseases and mortality from metabolic diseases, such as type 2 diabetes." (PMID 30838536, 2019). "Among the available medications for treating metabolic disorders, only Saroglitazar has a dual peroxisome proliferator-activated receptor ɑ + γ action that can reduce high triglycerides and improve insulin sensitivity." (PMID 31886093, 2019). "Diabetes mellitus is one of the most common metabolic diseases and a major disorder of insulin regulation with increasing incidence." (PMID 31396030, 2019). "T2D is a metabolic disorder characterized by elevated fasting plasma glucose levels, increased insulin levels, insulin resistance, and beta cell dysfunction with the majority of changes occurring 5–10 years before clinical diagnosis." (PMID 31555072, 2019). "In summary, these findings suggest that ADF combined with a low‐carbohydrate diet is effective for weight loss, weight maintenance, and improving certain metabolic disease risk factors such as LDL cholesterol, blood pressure, and fasting insulin." (PMID 31890243, 2019). "T2D is a common endocrine and metabolic disorder characterized by pancreatic β-cell dysfunction in response to elevated blood glucose levels, insulin resistance, and the failure of peripheral tissues in response to physiological levels of insulin." (PMID 31141089, 2019). "Dysfunction of mitochondria results in detrimental effects on adipocyte differentiation, lipid metabolism, insulin sensitivity, oxidative capacity, and thermogenesis, which consequently lead to metabolic diseases." (PMID 31590292, 2019).
metabolic disorders (continued). "Administration of insulin, the most powerful metabolic promoter, can improve the metabolic disorders (dysmetabolisms) of various origins." (PMID 31089886, 2019). "T2DM is one of the most common metabolic disorders characterised by resistance to the action of insulin (IR), increased rates of endogenous glucose production, reduced insulin secretion, and β-cell dysfunction." (PMID 31097962, 2019). "Elevated levels of circulating BCAAs are associated with suppressed mitochondrial β-oxidation, reduced glucose tolerance, increased insulin resistance, and increased de novo lipogenesis, making BCAAs a potential biomarker of metabolic disease." (PMID 31555072, 2019). "T2DM is a metabolic disorder characterized by chronic hyperglycemia due to the resistance of target tissues to the metabolic action of insulin and dysfunction of pancreatic β cells." (PMID 31117294, 2019). "Adiponectin is an adipokine that regulates apoptosis, glucose and lipid metabolism, and insulin sensitivity in metabolic diseases." (PMID 31222110, 2019). "It is well established that T2DM is a complex multifactorial and polygenic metabolic disorder characterized by impaired insulin secretion and reduced sensitivity to the peripheral actions of insulin." (PMID 31787898, 2019). "Type 2 diabetes (T2D) is known as a metabolic disorder in which blood sugar levels rise due to both insufficient insulin production and resistance to insulin." (PMID 32802088, 2019). "The protective function of antagomiR-103 and -107 on systemic glucose metabolism and insulin sensitivity has been recently established for metabolic disease." (PMID 30731323, 2019). "In this present study, it was found that the excessive backfat thickness in sows during late pregnancy exacerbated the metabolic disorders in sows, including insulin resistance, systemic inflammation, and oxidative stress in sows during perinatal period." (PMID 31881697, 2019). "A large body of evidence indicates that in both horses and humans, metabolic disorders are usually accompanied by lipotoxicity in insulin-sensitive tissues, including liver." (PMID 31771123, 2019). "inversely correlated with inflammation, altered adipose tissue metabolism, and metabolic disorders, which played an important role in improving the insulin sensitivity." (PMID 30733971, 2019). "Increased SCD1 activity has been related to metabolic disorders; mainly alterations in lipogenesis and insulin regulation in both adult humans and pigs." (PMID 31284510, 2019). "In metabolic diseases involving insulin modulation on the other hand, muscles are differentially affected depending on their relative abundance of glycolytic and oxidative fibers." (PMID 30449736, 2018). "Brown adipose tissue is a promising therapeutic target in metabolic disorders due to its ability to dissipate energy and improve systemic insulin sensitivity and glucose homeostasis." (PMID 29472592, 2018). "In humans, increased desaturation index and SCD1 activity have been related to metabolic disorders, like alterations in lipogenesis and insulin regulation." (PMID 29534532, 2018). "It is important to note that reducing glucocorticoid signaling in animal models of metabolic disorders usually improves their metabolic profiles and insulin sensitivity." (PMID 30310815, 2018). "There is evidence that impairment of the insulin regulation of energy metabolism is considered to be an etiologic key factor for metabolic diseases." (PMID 30103741, 2018). "The findings not only uncover a novel function of PRKD2 in regulating insulin secretion but also reveal a potential therapeutic target for metabolic diseases." (PMID 29789568, 2018). "Nutritional excess is a major forerunner of metabolic disease, enhancing the secretion of insulin from pancreatic β cells while attenuating the metabolic actions of insulin in the liver, skeletal muscle, and adipose tissue." (PMID 30692925, 2018).
metabolic disorders (continued). "By contrast, germline or cell-specific overexpression of SIRT1 or SIRT6 were reported to expand lifespan and defense metabolic diseases in insulin-dependent and independent manners." (PMID 30574122, 2018). "Here we report a small molecule analog of NA, JBSNF-000088, that inhibits NNMT activity, reduces MNA levels and drives insulin sensitization, glucose modulation and body weight reduction in animal models of metabolic disease." (PMID 29483571, 2018). "Gut microbiota-derived endotoxin-induced metabolic disorders were evaluated by glucose and insulin tolerance test, gut permeability, Western blot and histological analysis." (PMID 29899272, 2018). "T2DM is a metabolic disorder with chronic hyperglycemia due to impaired insulin secretion and decreased insulin sensitivity of multiple etiologies." (PMID 30037028, 2018). "In previous studies, it has been reported that both Akt and AMPK signaling are critical for controlling metabolic disorders, especially in the insulin signaling cascade through glucose transport." (PMID 29967664, 2018). "Type-1 diabetes (T1D) is a metabolic disease involving the autoimmune destruction of insulin-producing pancreatic beta cells." (PMID 29765386, 2018). "T2DM is a metabolic disorder, characterized by dysregulation of carbohydrate, lipid, and protein metabolism as a result of impaired insulin secretion, insulin resistance, or both combined." (PMID 30510625, 2018). "We therefore postulate that a dysregulation of the mitochaperone network directly affects brain function and insulin sensitivity, acting as a percursor event for the development of neurodegenerative and especially metabolic diseases." (PMID 29755410, 2018). "We have studied the autoimmune-glucose related factor in a subset of patients with reproductive failure (RIF and RM), family history of metabolic disorders, normal BMI, normal fasting plasma glucose and low insulin levels after OGTT." (PMID 30346951, 2018). "Genus Akkermansia was involved in the enterocytes proliferation of the colonic wounds and reversing high-fat diet induced metabolic disorders, including fat-mass gain, adipose tissue inflammation and insulin resistance." (PMID 30356845, 2018). "DM2, a global public health problem, consists of a heterogeneous group of metabolic disorders that presents chronic hyperglycemia as a result of defects in the action or the insulin secretion." (PMID 30356347, 2018). "First, uric acid can contribute to fructose-induced metabolic disorders by impairing endothelial function, thereby decreasing insulin sensitivity by preventing insulin-induced muscle vasodilation." (PMID 30200408, 2018). "Studies in animal models of metabolic disorders frequently demonstrate that suppressing glucocorticoid signaling improves insulin sensitivity and metabolic profiles." (PMID 30310815, 2018). "The liver, as the central organ responsible for maintaining lipid and glucose hemostasis in the body, plays a crucial role in insulin sensitivity and metabolic diseases." (PMID 30574122, 2018). "This leads to diminished insulin sensitivity, and increments in both body and fat mass, and metabolic diseases." (PMID 30147656, 2018). "It was also suggested that metabolism disorder likely occur considering the sustained expression changes of insulin." (PMID 29382883, 2018). "Clinically, DM refers to a group of metabolic diseases in which there is a chronic hyperglycemic condition as a result of defects in insulin secretion, insulin action or both." (PMID 29378549, 2018). "Seventh, alterations in the competitive advantages in skeletal muscle-cells (e.g., decrements in insulin sensitivity) are the major driver of metabolic diseases." (PMID 30147656, 2018). "Excess body fat reduces insulin sensitivity, thereby increasing the prevalence of the metabolic diseases." (PMID 29986458, 2018).